IL6 (interleukin 6)
Diseases named in the same sentence as IL6 in open-access papers (continued):
Sharing a sentence is not in itself a finding about the gene and the disease.
kidney disease (continued). "Transgenic mice that constitutively express the IL-6 in the liver and secrete it into the blood could develop a progressive kidney disease, resulting in serum protein overload in the kidney damage." (PMID 35386695, 2022). "IL-6 may be involved in fibrosis and tissue damage, as identified in angiotensin II-induced renal disease models." (PMID 35054831, 2022). "IL6 was demonstrated to contribute to renal diseases like FSGS42." (PMID 33633212, 2021). "PM2.5 induces early tubular epithelial injury by upregulating IL-6/STAT3 pathway and promotes EMT of renal tubular cells, suggesting that exposure to PM2.5 may increase the risk of developing kidney disease." (PMID 34884542, 2021). "Due to the key role of IL-6 in kidney diseases, the impact of targeting IL-6 has been studied." (PMID 34307414, 2021). "Importantly, both IL-6 and IL-18 are upregulated by nuclear factor-κB (NF-κB) activation, triggering inflammation in cardiovascular and renal diseases." (PMID 34830289, 2021). "IL-6-associated and CRP-associated metabolites including pseudouridine, l-phenylalanine, and p-hydroxyphenylacetic acid were reported to be associated with renal disease, which were seen obviously abundant in the serum instead of GCF in the ESRD patients." (PMID 33903806, 2021). "The contributions of Th2 response to renal disease activity and LN development include the IL-6 and IL-4 production by activated basophils, which leads to autoantibody deposition in the kidney, increasing in a positive feedback loop the Th2 response, and B cell activation." (PMID 35005031, 2021). "Furthermore, the impact of lipid accumulation in renal structures for the development of renal disease, namely as inductor of inflammatory markers (such as IL-6), should be further elucidated." (PMID 32218109, 2020). "The worsened kidney disease in podocyte-specific C/EBP-α knockout mice was associated with heightened activation of NF-κB and glomerular production of MCP-1 and IL-6 and with increased number of infiltrating F4/80-positive macrophages in the renal tubulointerstitium." (PMID 27644413, 2016). "Toll-like receptor 9 (TLR-9) a receptor for CpG DNA is involved in activation of immune cells in renal disease and may contribute to chronic inflammatory disease progression through an interleukin-6 (IL-6) dependent pathway." (PMID 23472199, 2013). "Studies also suggest that IL-6 plays a key role in the development of renal disease." (PMID 22567283, 2012). "However, orthopaedic surgery and kidney disease were negatively associated with commencing non-anti-IL-6 bDMARDs, which highlights the impact of comorbidities on starting treatment." (PMID 39698233, 2025). "Therefore, IL-6 might have both pro-inflammatory and anti-inflammatory functions in different kidney diseases." (PMID 32028746, 2020). "However, some studies indicate that IL-6 has anti-inflammatory effects in kidney diseases." (PMID 32028746, 2020). "IL-6 blockade may improve renal disease and delay LN onset in experimental models." (PMID 30207171, 2018). "However whether a TLR-9/IL-6 signal amplification loop such as that which regulates B cell proliferation is active in patients with renal disease remains to be investigated." (PMID 23472199, 2013). "Several reviews have highlighted its effects on renal inflammation and fibrosis, elucidating its impact on inflammatory factors such as TNF-α, IL-1β, IL-6, and the TGF-β-Smad pathway, which contribute to fibrosis during kidney disease progression." (PMID 40442892, 2025). "Hence, urinary IL-6 levels could be a valuable prognostic marker in kidney disease progression." (PMID 37189804, 2023). "Kidney disease represents a state of chronic inflammation arising from an increase in proinflammatory mediators, such as TNF-α, CRP, and interleukin-6." (PMID 37096248, 2023).
kidney disease (continued). "Patient characteristics, including sex, age, body mass index (BMI), etiology of primary renal disease, basic monthly biochemical data, ROS, SOD3, IL-2, IL-6, and IL-18, were analyzed." (PMID 35740095, 2022). "NF-κB, a transcription factor, is closely involved in the regulation of renal disease progression, as it promotes the transcription of pro-inflammatory cytokines, such as TNF-α, IL-6, and ICAM-1." (PMID 35295738, 2021). "Increased levels of interleukin-6 (IL-6) and tumor necrosis factor-alpha (TNF-α) involved in the inflammatory response predict poor outcome in patients with renal disease." (PMID 33375198, 2020). "It has been determined that pro-inflammatory cytokines and chemokines such as TNF-α, IL-1β, IL-6, IL-8, and MCP-1 are involved in the development of kidney diseases." (PMID 32028746, 2020). "Being involved in a lot of inflammatory diseases, IL-6 and RANTES obviously exhibit their pro-inflammatory and chemoattractant potential also in renal disease." (PMID 33070237, 2020). "The elevation of pro-inflammatory cytokines such as IL-1β, IL-6 and TNF-α is common in CKD (Furuichi, Kaneko & Wada, 2009) and has been used as a predictor of mortality in patients with kidney disease." (PMID 31275747, 2019). "TNF-α: tumor necrosis factor alpha; IL-6: interleukin 6; CRP: ultra-sensitive C-reactive protein; Hcy: homocysteine; KDQOL-SF 36: kidney disease quality of life short form 36 questionnaire." (PMID 29694512, 2018). "MCP-1 is the only known inflammatory marker showing increased levels in early HFD-induced kidney disease, which further recruits macrophages that enhance the release of inflammatory mediators, including TNF-α and IL-6." (PMID 26291618, 2015). "In active renal disease patients, the IL-1β levels were positively correlated with SLEDAI score (r = 0.33, P < 0.001) compared with TNF-α (r = 0.18, P = 0.001) and IL-6 (r = 0.11, P = 0.01)." (PMID 25548434, 2014). "Previous studies have shown that reducing IL-6 and CRP levels may help mitigate inflammatory responses and improve disease outcomes in kidney diseases." (PMID 40717986, 2025). "Furthermore, Klotho alleviates cyclosporine A-induced nephropathy in vivo and in vitro models by blocking the PDLIM2/NF-κB pathway, which reduces the level of IL-8, IL-6, and IL-12." (PMID 40119098, 2025). "The expression of the pro-inflammatory cytokines TNF-α and IL-6 was similar between patients with and without DM in the early stages of kidney disease." (PMID 36232497, 2022). "In addition, our experiments show that CaD prevents the increase and upregulation/activation of several pro-inflammatory cytokines (IL-6, CXCL1, IL-1ß, TNF-α, and MCP-1) that play a significant role in renal-disease progression." (PMID 31935212, 2020). "Significant differences in serum levels of IL-18 were observed between the patients and control subjects, whereas that of IL-6 was not different between the two groups, although patients with nephropathy showed higher levels." (PMID 26239462, 2015). "On the other hand, it has been shown that overload of albumin in the proximal tubule promotes tubule interstitial injury leading to progression of renal disease through different pathways, including the accumulation of pro-inflammatory chemokines and cytokines such as TNF-α and IL-6." (PMID 24736406, 2014). "The degree of macrophage infiltration into the kidney is a major parameter used to predict the progression of renal disease, and activated macrophages express several inflammatory mediators, including TNF-α and IL-6, which play important roles in the pathogenesis of cisplatin-induced renal injury." (PMID 23476708, 2013). "Moreover, circulating IL-6 levels in patients with DKD are elevated compared to those in diabetic individuals without kidney disease." (PMID 39749325, 2024).
kidney disease (continued). "For renal disease, despite the fact that the exact mechanism has not been identified yet, the mutual inflammatory cytokines (CRP, IL-1, IL-6 and TNF-α) can invade renal tissue causing interstitial fibrosis, tubular injury and infiltration of different inflammatory cells." (PMID 37957565, 2023). "This may inhibit the signaling process mediated by IL-6, including the phosphorylation of STAT3, which is consistent with the view that targeting IL-6-dependent signaling can alleviate the harmful effects of kidney disease." (PMID 38179188, 2023). "However, recent studies have indicated that the role of IL-6 in the development of kidney disease is not fully understood." (PMID 35054831, 2022). "Moreover, oxidized albumin in kidney disease patients is independently correlated with higher plasma levels of transforming growth factor beta (TGF-β1), tumor necrosis factor (TNF-α), and interleukin (IL)-1β and IL-6." (PMID 33800425, 2021). "Although our study was conducted in a tertiary hospital in which patients were referred from several major regions in the country, our data showed common findings with the previous study; the correlation of IL-18 with renal disease activity and IL-6 with the non-renal disease have been described." (PMID 31842967, 2019). "Similarly to TNF-α, IL-6 levels are also higher in patients with DN in comparison with diabetes mellitus patients without nephropathy." (PMID 25785280, 2015). "Anecdotal reports in subjects without renal disease have suggested successful reversion of critical cases by non-selective (glucocorticoids, Intravenous immunoglobulin) or selective immunosuppression, i.e. interleukin 6 (IL-6) antagonism, mostly used as bail-out procedures." (PMID 33289854, 2021).
infectious disease (160 papers, 2012 to 2025). A disorder directly resulting from the presence and activity of a microbial, viral, or parasitic agent in humans. "Second, we did not incorporate other markers that have been associated with the outcomes of infectious diseases including cytokines (e.g., IL-6)." (PMID 38639116, 2024). "Increased systemic level of IL-6 level has been associated with various infectious and non-infectious disease pathologies and we have already reported it as an extensive soluble mediator of gut-brain axis dependent neuroinflammation." (PMID 35799048, 2022). "Interleukin-6 levels are associated with the severity of the infectious disease and the risk of complications." (PMID 35327350, 2022). "Taken together, we should bear in mind the possibility that DKA after infectious disease causes cytokine storm with elevated IL-6 levels and that such cytokine storm leads to the onset of ARDS." (PMID 35357353, 2022). "Considering the known plethoric effects of IL-6 on immunological outcomes, we expect polymorphisms at these loci to influence other infectious diseases." (PMID 34634929, 2021). "In summary, the impact of IL-6 polymorphisms in infectious diseases varies depending on the causative pathogens and ethnicities." (PMID 34634929, 2021). "Some of these had been previously associated to a worse prognosis in HIV and other infectious diseases, or related to inflammatory status (IL-6, CD14, CD163, IRAK-M, and TNFα)." (PMID 34211989, 2021). "For example, IL-6 promoter SNP rs1800796, which is highly prevalent in Asia, has been proposed to explain ethnic-specific susceptibility to some infectious diseases." (PMID 34634929, 2021). "Lower TLR-induced production of pro-IL-1β and IL-6 in innate immune cells during early infancy likely contributes to suboptimal vaccine responses and infectious diseases susceptibility." (PMID 24205068, 2013). "In addition, the blockade of IL-6 carries the risk of infectious diseases as observed during Siltuximab treatment of multiple myeloma." (PMID 39518029, 2024). "Further studies will need to clarify whether the higher risk for a severe disease course with lower baseline IL-6 levels may also extend to other infectious diseases." (PMID 39062668, 2024). "Increased levels of inflammatory cytokines, primarily IL-1α and IL-6, may be associated with periodontal, oncological, and infectious diseases." (PMID 39338495, 2024). "Furthermore, 96 blood indicators associated with infectious diseases were also measured, e.g., IL-6, IL-2R, and d-dimer." (PMID 36233840, 2022). "There are contradictory reports about the role of IL-6 polymorphisms in infectious diseases." (PMID 27834822, 2016). "Especially, elevated plasma IL-6 levels may be associated with autoimmune and infectious diseases." (PMID 39065221, 2024). "Further visceral adipose tissue produces more cytokines including tumor necrosis factor α and interleukin 6 and 1β, which weaken the immune response against infectious diseases." (PMID 41003144, 2025). "IL-6 is a proinflammatory cytokine that is involved in multiple infectious diseases and can also exhibit anti-inflammatory effects." (PMID 39779607, 2025). "The pro-inflammatory cytokine IL-6 has potential as a biomarker in infectious disease as it increases earlier than PCT and CRP, potentially allowing for early detection." (PMID 38921759, 2024). "While most of the cytokines quantified in this study displayed increasing levels in the infectious disease group compared to the remaining groups, IL-6, a pro-inflammatory cytokine, was the exception and showed decreasing levels." (PMID 39328992, 2024). "IL-6, a significant inflammatory cytokine, plays a crucial role in certain severe infectious diseases where it triggers a cytokine storm." (PMID 38822405, 2024). "Deficiencies in crucial cytokines, such as IL-6, IL-1β, and TNF-α, have been linked to severe infectious diseases." (PMID 38213288, 2024).
infectious disease (continued). "The differential patterns observed in arachidonic acid, IL-6, and CRP levels among the infectious disease groups suggest distinct immunological signatures associated with each pathogen." (PMID 39066228, 2024). "IL‐6 is an inflammatory factor that can be used for early diagnosis, disease assessment, treatment efficacy monitoring, and prognosis evaluation in infectious diseases." (PMID 40125250, 2024). "Interleukin 6 (IL-6) is pleiotropic cytokine with pathological pro-inflammatory effects in various acute, chronic and infectious diseases." (PMID 37754132, 2023). "When the immune system is activated under various conditions, for example, by injury, infectious disease, or surgery, IL-6 levels increase due to its production by monocytes and macrophages." (PMID 37568571, 2023). "In vitro, macrophages with TET2-repressing mutations expressed the pro-inflammatory IL-1β, IL-6 and inflammasome NLRP3 in a pattern typically associated with macrophage activation in infectious diseases." (PMID 36835370, 2023). "The WBC count, and CRP, PCT, TNF‐α, and IL‐6 levels are the most common clinical indicators to assess infectious diseases." (PMID 37102655, 2023). "Although elevated levels of IL-6 and CRP can also be caused by various infectious diseases, our study suggests that PE should also be considered in children with these markers." (PMID 37474910, 2023). "Infectious diseases are identified by triggering inflammatory genes such as nuclear factor kappa B (NF‐kB) that in turn activates IL‐6 and TNF‐α." (PMID 37025056, 2023). "As a matter of fact, STAT3 is the most involved transducer activated by acute inflammatory stimuli that increase the transcription of IL-6, one of the main players in the acute phase response during inflammation and infectious diseases." (PMID 35408963, 2022). "IL-6 is an acute-phase response inducer in the context of elevated stress levels and inflammation or infectious disease." (PMID 36364860, 2022). "Mediators of changes in thyroid function during acute and chronic illnesses are much varied, but pro-inflammatory cytokines including IL-1, IL-6 and TNF-α have been implicated in several infectious diseases." (PMID 34650659, 2021). "More specifically, colchicine is a valuable drug for various infectious diseases triggered by over-activation of the IL-1/IL-6 pathway." (PMID 34812049, 2021). "IL-6 and IL-10 are two essential components of inflammatory response in almost all infectious diseases released by a range of different cells." (PMID 34088317, 2021). "IL-6 levels can assist in understanding the progression of infectious diseases and the response to treatment." (PMID 33693014, 2021). "IL-6 plays a role in host defense against infectious diseases while IL-12 is naturally produced by macrophages, neutrophils, dendritic cells, and B-lymphoblastoid cells." (PMID 34834244, 2021). "Studies have shown that both IL-1ß and IL-6 are very important proinflammatory interleukins involved in the pathogenesis of infectious diseases." (PMID 33291232, 2020). "Dynamic observation of IL-6 levels can assist in understanding the progression of infectious diseases and the response to treatment." (PMID 32754224, 2020). "IL-6 is a biomarker in septic patients, however, IL-6 levels are also upregulated in other non-infectious diseases." (PMID 29207683, 2017). "The depressive signs that occur in infectious diseases are related to the secretion of cytokines IL-1, IL-6 and TNFα." (PMID 28278190, 2017). "We think that we find a target to break the immune tolerance of IL-6 and a new way to control the clinical infectious disease." (PMID 25762865, 2015). "The severity of multi-organ function injury and case fatality rate are positively correlated with the plasma levels of inflammatory medium, and IL-6 is the main member of the cytokine network, possibly playing a significant role in various infectious diseases." (PMID 27602373, 2014).